DGKA (diacylglycerol kinase alpha)
Diseases named in the same sentence as DGKA in open-access papers (continued):
Sharing a sentence is not in itself a finding about the gene and the disease.
cancer (continued). "Therefore, DGKα generates distinct PA species in different cells, and the differences in the PA molecular species may account for the opposing functions of DGKα in cancer and T cells." (PMID 32947951, 2020). "In addition to being expressed in cancer cells, DGKα is highly expressed in T cells." (PMID 32947951, 2020). "Thus, DGKα appears to be both pro- and anti-tumoral depending on cancer cell-context." (PMID 32962151, 2020). "Indeed, DGKα inhibitors in vitro and in vivo could suppress cancer cell proliferation." (PMID 38716625, 2024). "Therefore, the inhibition of DGKα activity may suppress cancer progression." (PMID 36791913, 2023). "Given the new report and its potential implications, further work is needed to determine how DGKα inhibition directly affects macrophage phenotype and activity in the setting of GBM and other cancers." (PMID 35267577, 2022). "While all of this is preliminary, the effects of DGKα inhibition on angiogenesis are intriguing and merit further investigation in GBM and other cancer models." (PMID 35267577, 2022). "Those DGKα inhibitors are active in a lymphocyte based XLP-1 assay and in a cancer cell migration assay, holding the promise for a potential therapeutic application." (PMID 31690133, 2020). "Kaplan–Meier analysis revealed worse recurrence‐free survival and cancer‐specific survival rates in DGKα‐positive patients compared to DGKα‐negative patients (p = 0.036 and = 0.003, respectively)." (PMID 40013327, 2025). "Notably, we previously showed that top genes of this program (LDHB, GSTK1, DGKA, APRT, MGAT4A, and NMRK1) are predictive of the response of patients with cancer to ICIs." (PMID 40187353, 2025). "Inhibition of DGKα induces apoptosis in DGKα‐expressed cancer cell lines regardless of their origins." (PMID 38716625, 2024). "Therefore, it is possible that SFA- and/or MUFA-containing PAs produced by abundant DGKα can interact with and activate HSP27 in cancer cells as well and, consequently, induce cancer cell proliferation and cancer progression." (PMID 36791913, 2023). "DGKα inhibition may in fact lend itself to numerous synergistic combinations with other anti-cancer drugs, for GBM and other cancers as well." (PMID 35267577, 2022). "Combining DGKα inhibition with immunotherapies may be particularly promising for GBM and other immunologically cold cancers." (PMID 35267577, 2022). "The broad signaling effects of DGKα inhibition, as well as preferential activity against the treatment-resistant mesenchymal phenotype in GBM and other cancers, could translate to a host of promising anti-GBM combinations with a DGKα inhibitor." (PMID 35267577, 2022). "Fulfilling the potential of DGKα inhibition for GBM and other cancers will likely require the development of new small-molecule inhibitors, but such work is underway and in the meantime there may be utility in a repurposed drug such as ritanserin." (PMID 35267577, 2022). "The toxic effect is selective to cancer cells as only cancer cells (not normal cells) showed increased apoptosis by downregulation of DGKα activity." (PMID 36358678, 2022). "DGKα inhibition may also provide traction against a challenging and common resistance mechanism and subtype found in GBM and other cancers as well—the mesenchymal subtype." (PMID 35267577, 2022). "The upregulated DGKα expression is required for the growth and survival of highly metastatic cancer cells but not for those of non-transformed primary cells." (PMID 32962151, 2020). "In contrast to cancer cells, DGKα facilitates the immune nonresponsive (nonproliferation) state known as T cell clonal anergy." (PMID 32947951, 2020). "It demonstrated its prevalent inhibitory activity against the sole DGKα (IC50 value of 15 μM reported) in a dose‐dependent manner, even if growing doses are able to affect the activity also of other isoforms, and therefore its repurposing for cancer treatment was proposed." (PMID 40859612, 2026).
cancer (continued). "In addition to cancer cells, DGKα is highly abundant in T cells and induces a nonresponsive state (anergy), which represents the main mechanism by which advanced cancers escape immune action." (PMID 34680338, 2021). "In addition to cancer cells, DGKα is highly abundant in T cells and induces a nonresponsive state (anergy), representing the main mechanism by which advanced cancers avoid immune action." (PMID 34680338, 2021). "In addition, two novel DGKα inhibitor compounds, namely 11 and 20 (with an IC50 of 1.6 and 1.8 μM respectively, thus representing the most potent DGKα inhibitors until now), decreased cell migration in cancer cells." (PMID 32722576, 2020). "Hence, small-molecule inhibition of DGKα is selectively toxic to human cancer cells but not normal human cells, thus making DGKα inhibition a promising therapeutic target." (PMID 32722576, 2020). "DGKα targeting might therefore represent a useful and non-explored approach to combine with and prevent resistance to anti-cancer therapies aimed to inhibit the PI3K/AKT axis." (PMID 25339152, 2014). "DGKα staining of cancer tissues from the patients was classified into three levels according to the staining intensity in the cancer cell cytoplasm, and cases in which cancer cells in the sections could not be judged to be specifically stained were defined as negative for staining." (PMID 38716625, 2024).
infection (2 papers, 2016 to 2019). The state of being infected such as from the introduction of a foreign agent such as serum, vaccine, antigenic substance or organism. "We demonstrated that simultaneous ablation of both DGKα and ζ (DKO) in naïve CD8 T cells resulted in severe impairment of expansion and functioning of effector CD8 T cells during primary responses to LM-OVA infection due to impaired recruitment to and priming in draining lymph nodes (dLNs)." (PMID 27014906, 2016).
animal disease (1 paper, 2021). "In animal disease models, DGKα inhibitors limit CD8+ expansion and immune-mediated tissue damage, suggesting the possibility of using inhibitors of diacylglycerol kinase as a new therapeutic approach." (PMID 34072296, 2021).
bacterial infection (1 paper, 2016). "Thus, although deficiency of either DGKα or ζ enhanced primary CD8 T cell responses to viral and bacterial infection, simultaneous loss of DGKα and ζ severely impaired CD8 cell expansion and memory formation." (PMID 27014906, 2016).
infectious disease (1 paper, 2021). A disorder directly resulting from the presence and activity of a microbial, viral, or parasitic agent in humans. "Given the role of macrophages in healing injury and combating infectious disease, DGKα inhibitors might find clinical applications in treating these pathologies as well." (PMID 34804012, 2021).
DGKA also shares sentences with these, for which no sentence is quoted: glioma (2 papers); lymphoma (2); pancreatic cancer (2); anaplastic large cell lymphoma (1); Bladder Cancer (1); brain glioblastoma (1); breast adenocarcinoma (1); cardiovascular disease (1); chronic kidney disease (1); colon adenocarcinoma (1); colorectal tumor (1); genetic diseases (1); Hypertension (1); immune dysfunction (1); intrahepatic cholangiocarcinoma (1); migraines (1); neurological disorders (1); periodontitis (1); pulmonary fibrosis (1); renal angiomyolipoma (1); Respiratory Diseases (1); schizophrenia (1); steatosis (1); T-cell lymphoma (1).